LEP (leptin)
Diseases named in the same sentence as LEP in open-access papers (continued):
Sharing a sentence is not in itself a finding about the gene and the disease.
asthma (continued). "Leptin is a hormone of great interest in airway remodeling in asthma, as its levels are known to be enhanced during allergic reactions." (PMID 35769576, 2022). "In the genetic correlation analysis, we found that adiponectin was only significantly associated with childhood-onset asthma, whereas CRP, IGF-1, leptin, and TNFR2 were only significantly associated with adult onset asthma." (PMID 36253437, 2022). "Exploring the correlations between leptin and immune cells is a prerequisite for a better understanding of the downstream mechanisms of asthma." (PMID 36551211, 2022). "Many studies described the immune cell and related cellular pathways activated by leptin, which are beneficial in asthma development and increasing exacerbations." (PMID 36551211, 2022). "Further work will be needed to fully elucidate the mechanisms through which leptin affects asthma and fibrosis." (PMID 35610699, 2022). "Most of them reported a stronger severity of asthma symptoms or higher exacerbations in obese patients, characterized by increased leptin levels and low adiponectin levels, compared with their non-obese counterparts." (PMID 36613991, 2022). "Previous studies about animal experiments have tried to decipher the relationship between leptin and obese asthma." (PMID 36551211, 2022). "Leptin impacts the pulmonary inflammation of obese asthma by activating the STAT3 signaling pathway." (PMID 36051916, 2022). "A relationship of leptin with asthma severity, reduction in spirometric parameters, and increased BMI has been shown." (PMID 36297006, 2022). "The correlations between leptin level and BMI or uncontrolled asthma score were more evident among female patients with asthma." (PMID 36551211, 2022). "Studies involved in the key cell reaction and animal models of asthma have provided vital insights into the proinflammatory role of leptin in asthma." (PMID 36551211, 2022). "Certain investigations are needed to explore the mechanisms of leptin in the complex process of asthma development and other phenotypes of asthma." (PMID 36551211, 2022). "Another longitudinal study followed leptin levels, lung function, exercise-induced bronchospasm, and asthma-related symptoms of post pubertal obese adolescents undergoing weight loss of interdisciplinary intervention." (PMID 36551211, 2022). "Despite the existing limiting factors, the results of this study support the relevant role of leptin in the pathophysiology of asthma in obese subjects." (PMID 36613991, 2022). "Some of the studies included in this meta-analysis involved pulmonary function tests, such as an FEV in one second (FEV1) and FVC/FEV1 ratio, and their correlation with leptin levels or severity of asthma." (PMID 36613991, 2022). "Epidemiological studies mainly demonstrated the correlation of leptin with asthma development from some perspectives." (PMID 36551211, 2022). "FEV1, total lung capacity, functional residual capacity, asthma control, and systemic inflammation markers (CRP and leptin) were improved in the asthma group with BS." (PMID 36551211, 2022). "In a population of 19 patients with asthma, the study manifested a reduction in systemic levels of leptin and an improvement in asthma activity scores after bariatric surgery through 1-year follow-up." (PMID 36551211, 2022). "From the extensive literature about the cellular role of leptin, we reported studies to address the pathophysiology of asthma." (PMID 36551211, 2022). "Studies involved in the cellular immune responses and asthma animal models have provided vital insights into the deleterious role of leptin in asthma." (PMID 36551211, 2022). "The levels of leptin were found to be higher in children with asthma compared with healthy controls." (PMID 35769576, 2022). "Recently, several studies showed that leptin was related to advanced asthma symptoms and airway hyperresponsiveness." (PMID 36551211, 2022).
asthma (continued). "The present work concluded in a systematic review and a meta-analysis to evaluate the potential relationship between the circulating leptin in obese patients and the severity of asthma." (PMID 36613991, 2022). "It was reported that exogenous administration of leptin increased the airway hyperresponsive of the asthma mouse model." (PMID 36551211, 2022). "The objective of our study is to review the present data supporting the pathological role of leptin in asthma, including studies from clinical cohort studies and animal models." (PMID 36551211, 2022). "In this perspective, the arguments about the different faces of leptin in asthma are provided to picture the potential directions, thus yielding a better understanding of asthma development." (PMID 36551211, 2022). "Leptin, a hormone derived from adipose tissue, is significantly increased in children with asthma and in obese people." (PMID 36297006, 2022). "Comparing serum leptin in overweight/obese asthmatic individuals with that in controls with a similar BMI would further confirm the effect of leptin on asthma." (PMID 35889925, 2022). "Visceral AT from obese subjects with asthma isolated at the time of bariatric surgery had significantly lower adiponectin, but higher leptin and CD68 (a macrophage marker) expression compared with control participants, and this was independent of BMI." (PMID 33418879, 2021). "From prior studies it has been observed that obese subjects with asthma have more circulating leptin and a reduction in the anti-inflammatory adipokine, adiponectin, than lean people with asthma [34,73, –, 75]." (PMID 34918742, 2021). "For these reasons, different studies have tried to elucidate the possible role of leptin in airway inflammation and asthma." (PMID 32630168, 2020). "Studies in utero have shown that maternal famine was associated with higher methylation of IL10, LEP, ABCA1, GNASAS, and MEG3 genes, compared to the same-sex unexposed siblings, potentially increasing risk of asthma later in life." (PMID 32047643, 2019). "There is evidence that leptin can upregulate cytokines such as IFNγ and IL-17 in asthma and can both promote and inhibit Th2 effector functions in vitro and in type 2 diseases such as asthma and allergic rhinitis." (PMID 30978945, 2019). "The excessive secretion of leptin in the body induces asthma symptoms through inhibiting the immune T‐cell function." (PMID 31152468, 2019). "This study aims to investigate the correlations of asthma in children with body mass index (BMI), adiponectin, and leptin." (PMID 31152468, 2019). "The study also found elevated plasma CRP and leptin levels in obese asthma adults, while serum tryptase concentrations remained unchanged across different age groups of obese individuals." (PMID 30450768, 2019). "The high value of BMI and leptin, along with low level of the adiponectin, indicates severe asthma in patients." (PMID 31152468, 2019). "Leptin is a dominant cytokine released by adipose tissues and is correlated to airway reactivity in obese subjects with asthma." (PMID 30832310, 2019). "Previous clinical studies showed increased leptin levels in serum of adult patients diagnosed with asthma and in children with atopic asthma as compared to healthy control groups." (PMID 30203371, 2018). "It seems that increased leptin level is specific for asthma, in particular, those with severe symptoms." (PMID 30203371, 2018). "Our previous study performed on LEP and LEPR gene polymorphism showed an association of rs13228377 polymorphism with childhood asthma with AA risk genotype and A risk allele in a cohort of Polish children." (PMID 30203371, 2018). "In vivo, splenic CD4+ T cells from high fat diet-fed mice (termed HFD mice) with plethoric leptin and exacerbated asthma symptoms, close to obese human subjects, express increased amounts of XBP1s relative to normal chow diet-fed group (termed ND mice)." (PMID 29891850, 2018).
asthma (continued). "The interesting observation from our study is that leptin level is significantly increased during asthma exacerbation suggesting its role in active inflammatory processes." (PMID 30203371, 2018). "Lung function, anthropometrics, maximal oxygen uptake (VO2max), asthma severity, fat percentage, and systemic markers (leptin, adiponectin, and CRP) were measured at baseline, 6 months, and 12 months." (PMID 30400197, 2018). "Evaluating three-way statistical interactions on a multiplicative scale between sex, acetaminophen use and polymorphisms in leptin (LEP) and leptin receptor (LEPR) genes on the risk of current asthma: results from the Isle of Wight study." (PMID 30231898, 2018). "Female asthmatics had higher leptin levels than males with asthma (31.6 ± 24.1 compared to 13.1 ± 11.9 ng/mL, p = 0.01)." (PMID 26770217, 2015). "Adiponectin has also been shown to play a role in animal models of asthma but, in contrast to leptin, this adipokine attenuates pulmonary inflammation." (PMID 26770217, 2015). "Later adipokines have also been linked to inflammatory lung diseases like asthma and COPD and the majority of the studies have concentrated on the role of leptin and adiponectin in these diseases." (PMID 24891763, 2014). "They found that leptin levels were increased in overweight/obese subjects regardless of asthma status (P = 0.013) but were significantly higher in those with asthma." (PMID 23710195, 2013). "It is possible that leptin expression in omental adipose tissue is a marker for other adipose tissue dependent effects that modify asthma." (PMID 24288549, 2013). "Those with asthma had increased macrophage infiltration of visceral adipose tissue (P < 0.01), increased expression of leptin (P < 0.01), and decreased adiponectin (P < 0.001) when controlled for BMI." (PMID 23710195, 2013). "Multiple regression analysis revealed that after adjustment for other adiposity measures such as BMI and serum leptin and adiponectin, low serum resistin concentrations were still strongly predictive of asthma." (PMID 24288549, 2013). "Much less data exists addressing a possible relationship between resistin and asthma than that existing for either leptin or adiponectin and asthma." (PMID 24288549, 2013). "In fact, low sputum adiponectin predicted asthma status better than other measures of adiposity including serum adiponectin, serum leptin, BMI, or DEXA measures of fat and lean mass in that study." (PMID 24288549, 2013). "Serum leptin levels in well controlled, partially controlled, and uncontrolled asthma groups were found to be 17.01 ± 14 ng/mL, 16.04 ± 14.52 ng/mL, and 22.25 ± 12.37 ng/mL, respectively." (PMID 24454412, 2013). "In summary, although leptin and its receptors are expressed in human airway cells, our understanding of the relationship between leptin and asthma is still evolving." (PMID 24288549, 2013). "The uncontrolled group had higher leptin and lower adiponectin levels compared to well and partially controlled asthma." (PMID 24454412, 2013). "Leptin alone induced production of proinflammatory cytokines from macrophages derived from overweight/obese subjects with asthma showing that macrophages from overweight/obese people with asthma are more sensitive to leptin." (PMID 23710195, 2013). "Leptin has been reported to be increased or normal in asthma, resistin either increased or decreased, and adiponectin either decreased or normal." (PMID 21615949, 2011). "In asthmatics, leptin correlated positively with asthma symptom score and negatively with lung function." (PMID 21615949, 2011). "Clinical studies provide confounding evidence to the mouse-model observation regarding the role of leptin in asthma." (PMID 21040518, 2010). "Studies further suggest a significant impact of leptin on specific respiratory diseases, including obstructive sleep apnoea-hypopnoea syndrome, asthma, COPD and lung cancer." (PMID 21040518, 2010).
asthma (continued). "Research data suggest that leptin/leptin receptor system expression and signaling is altered in the airways of patients with asthma and COPD." (PMID 21040518, 2010). "Measurements included plasma levels of leptin, adiponectin, exhaled breath condensates for 8-isoprostanes, exhaled NO, pulmonary function tests, and questionnaires regarding asthma severity and control." (PMID 17437645, 2007). "In conclusion, our pilot study provides reassuring evidence that short-term high-dose ICS therapy may not lead to significant changes in appetite, dietary intake, leptin levels, or body weight in adults with stable asthma." (PMID 40710443, 2025). "There may be a connection between the pathophysiology of asthma and the adipocytes, adiponectin, and leptin produced by the body." (PMID 40242447, 2025). "Thus, it was shown that leptin was inversely correlated with the severity of asthma, which was assessed by the level of FEV1 (r = −0.714, p = 0.001) and FVC (r = −0.740, p = 0.001)." (PMID 40361972, 2025). "Interestingly, OCSs have been shown to increase appetite, body weight, and circulating levels of leptin and adiponectin in patients with asthma and chronic obstructive pulmonary disease (COPD)." (PMID 40710443, 2025). "Asthma symptoms improved due to reduced fat cells, lower leptin, and higher adiponectin levels." (PMID 40242447, 2025). "Leptin levels are increased in overweight horses, but leptin’s association with asthma has not yet been studied." (PMID 38254421, 2024). "Asthma was associated with the increased expression of pro-inflammatory cytokines, including IL-2, IL-5, IL-13, IL-17A, IL-22, IL-33, and TNF-α, and reduced levels of anti-inflammatory cytokine, IL-10 and adipokine, leptin in the circulation." (PMID 39902293, 2024). "The precise mechanism by which leptin induces EMT in asthma remains unclear, but it may involve the activation of the ERK signaling pathway or PI3K/Akt-dependent pathway." (PMID 38562155, 2024). "Our findings have revealed that obese asthma patients, despite the basic anti-inflammatory therapy, had elevated levels of inflammatory markers in blood plasma such as leptin, tumor necrosis factor-α (TNF-α), interleukin-2 (IL-2), IL-4, and IL-17a, leukotriene B4 (LTB4), and thromboxane B2 (TXB2)." (PMID 37367676, 2023). "Some investigations yielded that leptin status was significantly higher in asthma cases than that in non-asthma controls, whereas some studies showed a null difference of leptin levels between asthma and controls." (PMID 36914629, 2023). "This suggests that long-term supplementation with AGs may have a beneficial effect on leptin levels in obese asthma patients by reducing the inflammation of adipose tissue." (PMID 37367676, 2023). "This study also suggested that metabolites secreted during pregnancy (e.g., serum leptin) may mediate asthma development in the offspring." (PMID 36984768, 2023). "On the other hand, only seven studies were recruited for the analysis of the difference of leptin level between severe and mild asthma among Caucasians, which may reduce the statistical power." (PMID 36914629, 2023). "We evaluated the predictive and prognostic value of leptin status in asthma." (PMID 36914629, 2023). "We detected the level of leptin in the serum of patients with asthma by ELISA." (PMID 37488474, 2023). "We searched the electronic databases for articles that determined the leptin level in asthma cases through May 2020." (PMID 36914629, 2023). "It was revealed that leptin could increase the production of Th17 cytokines, which was related to the severity of asthma." (PMID 37488474, 2023). "In T2-low asthma, macrophages recruitment is also driven by the epithelial release of CCL2 and CCL3, while in obesity-related asthma, leptin activates airway epithelial cells and induces the production of cytokines such as IL-8, further contributing to neutrophil recruitment." (PMID 35456002, 2022).
asthma (continued). "Adipose tissue secretes proinflammatory cytokines and mediators, including leptin, which may promote the development and severity of asthma in obese patients." (PMID 36613991, 2022). "Since little is known about how leptin influences asthma, it is also unclear how sex may affect leptin-induced changes." (PMID 35610699, 2022). "Among these studies, high leptin was identified frequently in patients with asthma." (PMID 36551211, 2022). "Leptin was reported to be related to body weight-gain-related asthma by regulating lung injury." (PMID 36551211, 2022). "Other hormones such as leptin have been linked to the sex differences in asthma in both obese and non-obese patients." (PMID 35769576, 2022). "However, most animal studies are based on eosinophil asthma, and few studies explored the role of leptin in neutrophil asthma mouse models, although obese asthma was seen more frequently in non-atopic asthma." (PMID 36551211, 2022). "This, taken together with the changes in AHR seen in male mice, suggests that leptin may play a greater role in modulating asthma outcomes in males compared to females." (PMID 35610699, 2022). "However, the role of leptin in neutrophil and eosinophil activation remains to be explained in obese asthma mice." (PMID 36551211, 2022). "There were a series of studies revealing the positive correlations between leptin and asthma severity, suggesting leptin could be used as a pro-inflammatory biomarker in severe asthma." (PMID 36551211, 2022). "This appears important as in patients with asthma, leptin induces inflammation in lung fibroblasts by enhancing the production of further pro-inflammatory chemokines and cytokines, which appears somewhat suppressed when a patient experiences leptin resistance." (PMID 34918742, 2021). "One has to keep in mind that leptin takes part in the pathophysiology of both asthma and obesity and that outcomes of these diseases may overlap, especially in the context of lung function." (PMID 34948451, 2021). "Notably, previous studies have shown that serum leptin levels are elevated in patients with asthma compared to healthy controls." (PMID 35046816, 2021). "Leptin levels may be an indicator of asthma control, as its levels rise during exacerbations in adults." (PMID 34948451, 2021). "Nevertheless, the findings of our study are in accordance with those of an important previous report indicating that elevation of leptin may be involved in the pathogenesis of asthma in a BMI-independent manner." (PMID 35046816, 2021). "However due to the shift in leptin and adiponectin levels in obese patients with asthma, the adipokines can mediate more inflammation and AHR." (PMID 34918742, 2021). "Increased leptin and IL-6 levels in asthma patients have recently been identified in several studies, strengthening the link of these pro-inflammatory cytokines with airway inflammation in asthma." (PMID 34921631, 2021). "We assessed how exogenous leptin influences the IL-33-induced asthma model." (PMID 34074279, 2021). "One possible explanation for the obese-asthma neutrophilic phenotype may be related to serum levels of leptin, a key player in body weight regulation, which increases helper T cell type 1 (Th1) inflammation." (PMID 32610544, 2020). "Children with uncontrolled asthma had higher leptin levels than those with controlled asthma." (PMID 33134805, 2020). "Less is known about leptin-mediated molecular mechanisms in human airway inflammation and asthma." (PMID 32630168, 2020). "BMI, adiponectin, and leptin have certain predictive values for the condition of asthma, suggesting they might be used as potential indicators for future treatment." (PMID 31152468, 2019). "Adiponectin, leptin, and BMI are involved in the pathogenesis of asthma in children, suggesting they might be therapeutic targets for clinical treatment." (PMID 31152468, 2019).